CXCL10 (C-X-C motif chemokine ligand 10)
Diseases named in the same sentence as CXCL10 in open-access papers (continued):
Sharing a sentence is not in itself a finding about the gene and the disease.
tumor (continued). "Particularly, intravesical instillation of VB-85247 induced elevated gene expression in the tumor-bearing bladders for IFNβ, CXCL10, CCL5, IL6, and TNFα at 4 hours after treatment, with the fold-induction of gene expression in the order of IFNβ > CXCL10 > CCL5 > IL6 > TNFα." (PMID 39700406, 2025). "Chemokines such as CXCL10 and CX3CL1 can attract NK cells that can directly kill tumor cells." (PMID 40145607, 2025). "Further, we co‐cultured LLC tumor cells with peritoneal macrophages at ratios of 1:1 and 3:1, stimulating them with CCM or CFM, respectively, and measured the expression levels of CD86, CD206, TNF‐α, and CXCL10." (PMID 40637137, 2025). "Moreover, our transcriptomic data further revealed that lacidipine regulated multiple immune‐related genes, significantly upregulating “hot” tumor‐related genes such as CCL5, CD274, CXCL10, and CXCL11, while downregulating the “cold” tumor‐related gene CCL2." (PMID 39585774, 2025). "However, chronic overexpression of CDC25C upregulates PD-L1 in tumor cells through the STAT3/IRF1 pathway, and promotes the recruitment of Tregs, MDSCs and M2-like macrophages (M2) via chemokines such as CXCL10." (PMID 41019083, 2025). "Moreover, investigations revealed that in the LLC tumor model, the knockdown of ORMDL3 led to a significant increase in the expression of ISGs, including Ccl5, Cxcl10, Tnf, and Il6, compared to the control group." (PMID 40126553, 2025). "Type-II interferon (IFN-γ) inflammatory signaling induces PD-L1 expression on cancer cells, conducive for tumor immune evasion, and at the same time upregulates chemokines such as CXCL9/CXCL10 that recruit CXCR3+ effector T cells as a cytotoxic response to cancer." (PMID 41440526, 2025). "Notably, genetic ablation of either CXCL10 or TLR4 significantly reduces tumor growth and systemic MDSC accumulation, illustrating the mechanistic diversity of CXCL10-mediated immunosuppression." (PMID 41516196, 2025). "CXCL10 facilitates the recruitment of CXCR3+ - CTLs, NK cells and Th1 cells into the tumor microenvironment, where they play an essential role in the recognition and destruction of tumor cells." (PMID 40760734, 2025). "Simultaneously, chemokines such as CXCL9, CXCL10, and CCL5 regulate T-cell recruitment, whereas LFA-1 and adhesion molecules like ICAM-1 govern their infiltration and retention within the tumour." (PMID 40361472, 2025). "Given that the recruitment of lymphoid cells still occurs in IFNγRKO tumours, the slight decrease in CXCL10 is unlikely to explain differences in microenvironment and milieu observed between WT and IFNγRKO tumours." (PMID 39746898, 2025). "Similarly, compared to CAF‐S4, CAF‐S5 also upregulates CCL4, CXCL9, CXCL10, CXCL11 and IL1RN suggesting that cytokine and chemokine transcripts are enriched in tumours with high CAF‐S1 and CAF‐S5 and low in the myCAF‐like subset CAF‐S4." (PMID 39743376, 2025). "Independent of the effects of T cell transfer, a set of genes characteristic of an IFNα response (for example, Irf7, Isg15 and Cxcl10) was higher in NTT TMEs than in RTT TMEs, which suggested that both IFN-I and IFN-II cytokines modulate an inflammatory TME in NTT tumours." (PMID 39604727, 2025). "Eosinophils can recruit tumor-specific CD8+ T cells into the tumor microenvironment by secreting chemokines such as CCL5, CXCL9, and CXCL10, and induce macrophage polarization toward the M1 phenotype, thereby enhancing the immune system’s ability to recognize and destroy tumor cells." (PMID 39949762, 2025). "The results revealed that irradiation increased the levels of chemokines involved in the migration of T cells (e.g., CXCL10, CCL2, CCL3, and CCL5) but decreased the levels of proangiogenic factors (e.g., VEGF and basic FGF), which facilitate T cells infiltration into the tumor bed." (PMID 40510363, 2025).
tumor (continued). "Beyond CXCL10’s role as a chemoattractant for immune cells, it also orchestrates their spatial organization and activation within the TME to ensure an effective anti-tumor response." (PMID 41516196, 2025). "Furthermore, DC-derived chemokines, including CXCL9 and CXCL10, guide Teff cell trafficking to tumor sites through CXCR3 receptor binding, facilitating tumor infiltration." (PMID 41281945, 2025). "In tumor cells, METTL3 and METTL14 can inhibit the expression of CXCL9 and CXCL10." (PMID 39726589, 2024). "We show here that COX2 expression at the tumor margin limits CD8+ T-cell infiltration into the tumor core, which involves at least in part reduced cytokine and chemokine expression (IRF8, CLEC9a, CXCL9, CXCL10, CXCL11, and IL27) that promotes directional immune cell migration." (PMID 39356141, 2024). "Mechanistically, the immune effector stromal predilection appears driven by low tumor cell MHC class II (HLA-DR), CXCL9, and CXCL10 expression as those tumors with increased tumor cell expression of each of these mediators correlated with significant increases in T cell infiltration." (PMID 38822345, 2024). "Indeed, anti-tumor immunity in MMRd cancers also depends on the magnitude of cGAS/STING activation and subsequent expression of CCL5 and CXCL10 in the tumor microenvironment (TME), which influences CD8+ T and NK cell infiltration." (PMID 39544936, 2024). "The results showed that in the group with high CXCL10 expression, there were higher abundances of CD8 T cells, CD4 T cells, and M1 macrophages (p < 0.05), all of which play important roles in anti-tumor immune processes." (PMID 38720149, 2024). "Moreover, radiotherapy stimulates the release of chemokines such as CXCL9, CXCL10 and CXCL16 from tumor cells and stromal cells, which increase the infiltration of intratumoral NK, DC, and T cells, leading to enhanced anti-tumor immunity." (PMID 39712010, 2024). "CCL5, CXCL9, CXCL10, CXCL11, and CX3CL1 are involved in the recruitment of CD8+ T cells to tumours." (PMID 38291183, 2024). "Although CXCL10 was significantly increased in neutrophils in the liver metastases tumor in BT model mice, primary bile acid stimulation on neutrophils in vitro did not impact their expression level of CXCL10." (PMID 38951890, 2024). "Certain chemokines (such as CXCL9 and CXCL10) can promote anti-tumor immune responses, while others (like CCL2 and CXCL12) may facilitate tumor progression." (PMID 39030403, 2024). "However, prolonged exposure to interferon-gamma transforms teammates into adversaries, producing pro-tumorigenic effects through immunosuppression (PDL1, IDO1, Fas, and FASL), angiogenesis (CXCL9, CXCL10, CXCL11, IDO1, and iNOS), and tumor cell proliferation." (PMID 39835116, 2024). "Immunotherapeutic strategies that augment tumor cell expression of MHC class II, CXCL9, and CXCL10 may improve parenchymal trafficking of immune effector cells in ONB and augment immunotherapeutic responses." (PMID 38822345, 2024). "However, CXCL10/CXCR3 signaling promotes tumor cell proliferation, angiogenesis, and metastasis when mediated by an autocrine pathway in tumor cells." (PMID 39273452, 2024). "Notably, tumor derived expression of CXCL10 has been hypothesized to localize effector CD8 + T cells via their CXCR3 receptor to the tumor site, an interaction observed within our RDI network that exhibits anti-tumor properties and is associated with immunotherapy response." (PMID 39402030, 2024). "Moreover, eosinophils induced tumor cell killing in vitro through the production of CCL5, CCL9, and CXCL10." (PMID 39126091, 2024). "Results demonstrated that CXCL10 exhibited low expression in tumor cells with Smad4 high expression group, showing a negative correlation between Smad4 and CXCL10 expression." (PMID 39346534, 2024).
tumor (continued). "We suggest that CXCL10 attracts CD8+ T cells into the tumor, where they generate robust anti-tumor effects, although the enhanced T cell infiltration in the distant (uninfected) tumor would indicate the presence of an additional, broader immune mechanism." (PMID 39410025, 2024). "First, we found that OSU13-treated tumor cells activated a proimmunogenic transcriptional program that translated to increased secretion of chemokines CCL5 and CXCL10, which are known to recruit activated T cells and other immune effectors to the sites of inflammation." (PMID 38900577, 2024). "This shift from CCL5/CXCL9/CXCL10 to CXCL8/CXCL12/CCL22 production was attributed to NFκB-mediated induction of COX2/PGE2/EP4, along with upregulation of IDO1 and IL-10, further contributing to the immunosuppressive tumor microenvironment." (PMID 39409924, 2024). "In addition to facilitating effector T cell infiltration into the tumor, the CXCL9/CXCL10/CXCR3 signaling cascade is required for optimal T cell activation." (PMID 38518770, 2024). "Studies have indicated that CXCL10 may promote the expression of IFN signature genes and TAA, potentially facilitating T cell infiltration into the tumor, ultimately enhancing PD-L1 and PD-1 blockade therapy." (PMID 39777330, 2024). "One of these chemokines, Cxcl10, not only attracts CD8+ effector T cells to sites of inflammation, but also direct their polarization into highly potent effector T cells, to restrain tumor growth and enhance anti-tumor immunity." (PMID 38622609, 2024). "Immune cell profiles analysis revealed that IFNΒCOL01 increased CXCL10 and MHC-I expression in CD11b+ cells, which may contribute to tumor growth inhibition." (PMID 38995014, 2024). "Notably, CXCL signaling network exhibit heightened activity in mediating communication between CXCL10+ M1 macrophages and CD4+T cell, with significantly elevated activity within the tumor group compared to the normal group." (PMID 39170612, 2024). "CXCL9 and CXCL10, by binding to their receptor CXCR, can attract and activate anti-tumor immune cells such as CD8+ T cells and natural killer (NK) cells, thereby enhancing their ability to eliminate tumor cells." (PMID 38277205, 2024). "Treatment of cold tumors with some inhibitors such as Vps34 inhibitors can induce the release of inflammatory chemokines such as CCL5 and CXCL10 to recruit natural killer (NK) and CD8+ T cells to the tumor microenvironment, resulting in a better immunotherapeutic efficacy." (PMID 38953994, 2024). "Studies have proved that the expression levels of CXCL10 and CXCL9 in tumor may be correlated with a poor prognosis of overall survival." (PMID 38448514, 2024). "The limited infiltration of T cells into the tumor microenvironment may be downstream of the epigenetic silencing of key chemokines such as CXCL9 and CXCL10, which encompasses inhibitory histone modification and DNA methylation." (PMID 38665224, 2024). "Additionally, the combination of cisplatin and irinotecan enhances the secretion of IL‐1β, IL‐8 and CXCL10 through the cGAS pathway, which promotes the infiltration of CD8+ T cells and dendritic cells, effectively inhibiting tumour growth." (PMID 39270064, 2024). "Moreover, MLT also improved the secretion levels of TNF-α and CXCL10 in macrophages, and the exosomes secreted by MLT-treated GC cells promoted the recruitment of CD8+ T cells to the tumor site, hence inhibiting tumor growth." (PMID 38455041, 2024). "Notably, our computational analysis of this high-dimensional data suggests that the key changes correlating with inhibition of tumor growth include the downregulation of CCL-2, CCL-7, CCL-12, and the upregulation of CXCL-10, CCL-24, CXCL-12 and IL-3." (PMID 38575562, 2024).
tumor (continued). "By analyzing the effect of MAP2K3 expression levels on chemokines in the tumor immune microenvironment, the results showed elevated expression of several chemokines in the MAP2K3 high expression group; such as CXCL10, CCR5, CCR10, CCL5, CCL7, CCR2, and CCL22 (upper part)." (PMID 38938778, 2024). "Furthermore, EPI treatment effectively accelerated the secretion of Ccl5 and Cxcl10, promoting the recruitment of CD8+ T cells into the tumor." (PMID 38622609, 2024). "Remarkably, outgoing signals from CXCL10+ M1 Macrophages to B cells, CD4+T cell, CD8+T cells and Endothelial cell were more abundant and stronger in tumor group compared with normal group, while the output signal of SPP1+ macrophages cell was reduced in the tumor group." (PMID 39170612, 2024). "The study indicated that the anti-tumor immune responses following DDR targeting were observed to be mediated through the STING–TBK1–IRF3 pathway in SCLC, which stimulated secretion of the chemokines CCL5 and CXCL10." (PMID 38473324, 2024). "Remarkably, consistent with the great immunogenicity caused by the unstable genome profiles of the HRD group, HRD tumor epithelial cells exhibited high expression of immune chemokines that recruit immune cells to mediate antitumor effects, such as CXCL8, CXCL10 and CXCL11." (PMID 39136172, 2024). "Moreover, anti-tumor chemokine genes including CXCL9, CXCL10, CXCL11 and CXCL13 expressed higher in the high-necroptosis cohort." (PMID 39247606, 2024). "As CXCL10 is upregulated in GBM tissues and contributes to tumor progression and poor prognosis, inhibiting CXCL10 could be a viable treatment approach." (PMID 38461458, 2024). "For example, CXCL9 and CXCL10 are two important chemokines that are involved in antitumor immunity by binding to their receptor, CXCR3, which promotes the migration of T cells and NK cells into the tumor microenvironment." (PMID 39334957, 2024). "A CXCR3/CXCL9/CXCL10 axis could drive T cell infiltration into KPCY55 tumors of GPR55 KO mice, suggesting that GPR55 suppresses this pathway in PDAC, thereby promoting tumor growth." (PMID 39885986, 2024). "Moreover, we found that CD8+ T cells were recruited by CXCL10 in vitro, whereas SCH546738, an inhibitor of CXCR3, inhibited T cell migration and splenocytes-mediated anti-tumor effect." (PMID 38953994, 2024). "We report that in addition to attracting CXCR3+ T cells to tumor sites a key role of CXCL9 and CXCL10 is in inducing a self-feeding feedback loop that accelerates effector/cytotoxic activities of both CD4+ and CD8+ T cells while downregulating immunoregulatory protein TIM3." (PMID 39474427, 2024). "Several patients had postinfusion elevations of CXCL10 (IP-10), particularly patient 205 who restarted cytotoxic chemotherapy during the 6-week evaluation period because of the patient’s concern over a rising serum CEA tumor marker." (PMID 38754916, 2024). "Notably, treatment-induced tumor volume reduction correlated with decreased levels of CCL-2, CCL-7, and CCL-12 and increased levels of CXCL-10, CCL-24, CXCL-12, and IL-3." (PMID 38575562, 2024). "Eliminate pathogens and tumor cells through direct phagocytosis, activate T cells and NK cells through antigen presentation and secretion of proinflammatory cytokines and chemokines such as TNF-α, IL-1, and CXCL10." (PMID 38779867, 2024). "CXCL10 has been shown to enhance CAR-T cells’ proliferation and anti-tumor ability in vitro." (PMID 38475811, 2024). "Taken together, these results suggest that CXCL10 is involved in the regulation of cellular and humoral immunity in BLCA, and it may affect the tumor microenvironment of BLCA through multiple immune pathways." (PMID 38720149, 2024). "At the same time, the 1st released core was internalized by tumor cells and degraded by intracellular GSH, to realize a 2nd release of CDK4/6i in tumor cells, which induced an up‐regulated expression of CXCL10 and CCL5, and thus a significantly increased tumor infiltration of T cells." (PMID 38634209, 2024).
tumor (continued). "Additionally, an analysis of the tumor homogenates from treated vs. control mice via a multiplex cytokine panel highlighted intra-tumoral increases in CXCL9 and CXCL10." (PMID 38339310, 2024). "Similarly, the mono/macrophage cluster with higher expression of Cxcl10, which is a key chemokine responsible for CD8 T cell recruitment in tumor, are reduced in in Gpr84−/− mice." (PMID 38349405, 2024). "The use of the inhibitors SB02024 or SAR405 to inhibit VPS34 kinase activity led to increased levels of CCL5, CXCL10, and IFN-γ in the tumor microenvironment (TME), resulting in increased levels of tumor infiltration by NK cells and T cells in melanoma and colorectal cancer models." (PMID 39124918, 2024). "This may be due to significant increases in the calcium flux and ERK1/2 phosphorylation mediated by the CXCL10/CXCR3 pathway, which enhances tumor invasiveness." (PMID 39429695, 2024). "In addition, neutral sphingomyelinase 2 (nSMase2)-dependent EC activation has been shown to express chemokines, CX3CL1 and CXCL10, as well as the adhesion molecule VCAM1, to promote T cell migration into the tumor bed." (PMID 36901858, 2023). "METTL3/14 knockout in CRC enhanced the response to anti–PD-1 therapy in constructed Patient-Derived Xenograft (PDX) mice by increasing the infiltration of cytotoxic CD8+ T cells into the tumor cell and a marked increase in the concentration of IFN-c, Cxcl9, and Cxcl10 in the tumor microenvironment." (PMID 36960074, 2023). "In addition, the chemokine CXCL10 recruited CD4+ and CD8+ T cells to the tumor via CCR6+ type 3 innate lymphoid cells." (PMID 38075694, 2023). "On the CT26 and B16F10 tumor models, both local and systemic, CMP enhanced the expression of interferon‐β (IFN‐β), tumor necrosis factor‐α (TNF‐α), and CXCchemokineligand‐10 (CXCL10) proinflammatory cytokines, and promoted tumor invasion of CD8+ T cells, thus showing a good therapeutic effect." (PMID 37933288, 2023). "Three of them (CXCL10, CXCL6 and CXCL16) belong to the chemokine (C‐X‐C motif) ligand (CXCL) family, which are known to play key roles in inflammatory diseases, neoplastic transformation and tumour growth regulation." (PMID 36608258, 2023). "Therefore, RT potentially activates CD8+ T cells by inducing IFNs-mediated CXCL10 and ICAM-1 expression in tumors to enhance CD8+ T-tumor adhesion and recognition." (PMID 36688994, 2023). "Moreover, the tumor cell-derived CXCL6, CXCL2, and CCL20, TAM-derived CXCL9/CXCL10, and the stromal cell-derived CXCL12 also contributed to the accumulation of tissue-resident CD103+CD8+TILs in the TME." (PMID 37024870, 2023). "Meanwhile, since our previous study also showed that IRF1 recruited NK cells and CD8+T cells through CXCL10/CXCR3 axis, we investigated whether IRF1-MICA signaling recruited anti-tumor immune cells via the CXCR3 receptor." (PMID 36765808, 2023). "In addition to inducing effector Th1 cells, CXCL10 can also recruit CXCR3+CD8+T cells to the tumor site and promote these cells to produce Granzyme B, which enhances the anti-tumor effect." (PMID 36900218, 2023). "While the increase of the expression level of dog CCL5 was not significant, the expression of dog CXCL10 was significantly different between rMV-SLAMblind-treated tumor tissue and tumor tissue from the control group (p < 0.05)." (PMID 37875555, 2023). "Chemokine CXCL10, as an interferon-inducible protein, is most likely involved in the thermal-ablation-induced expression of CXCL10 by TAM1, which stimulates interferon secretion and recruits CXCR3+CD8+T cells to infiltrate into tumor tissues, thus exerting anti-tumor effects." (PMID 36900218, 2023). "DPP4 inhibitors preserve the activity of CXCL10 and make biologically active CXCL10 interact with its ligand (CXCR3) on NK and T cells, thereby increasing the chemotaxis of NK and T cells and further inhibiting tumor growth." (PMID 37115489, 2023).